NMT1 (N-myristoyltransferase 1)
Description:
Adds a myristoyl group to the N-terminal glycine residue of certain cellular and viral proteins. Also able to mediate N-terminal lysine myristoylation of proteins: catalyzes myristoylation of ARF6 on both 'Gly-2' and 'Lys-3'. Lysine myristoylation is required to maintain ARF6 on membranes during the GTPase cycle.
Synonyms: HsNMT1; NMT
Tractability: Small molecule: a structure with a bound ligand is known; a high-quality ligand is known; it has a high-quality binding pocket; it belongs to a druggable protein family. Antibody: UniProt places it where antibodies can reach, with high confidence; its Gene Ontology location is reachable by antibodies, with high confidence. PROTAC: ubiquitination databases record sites on it; its protein half-life has been measured; a small molecule that binds it is known.
Target class: Enzyme; Transferase
Chemical probes: DDD100097, DDD85646 (high quality), IMP-1088 (high quality)
Gene: Protein-coding gene on chromosome 17 (44,957,992 to 45,109,016, forward strand). Ensembl gene ENSG00000136448.
Subcellular location: Cytoplasm; Cytoplasm, cytosol; Membrane
Subcellular location (Human Protein Atlas): Cytosol; Plasma membrane
Pathways (Reactome):
Disease: Late Phase of HIV Life Cycle; Maturation of DENV proteins
Metabolism: eNOS activation
Programmed Cell Death: Activation, myristolyation of BID and translocation to mitochondria
Sensory Perception: Inactivation, recovery and regulation of the phototransduction cascade
Gene Ontology:
Molecular function: glycylpeptide N-tetradecanoyltransferase activity; myristoyltransferase activity; peptidyl-lysine N6-myristoyltransferase activity; protein binding; CoA-dependent peptidyl-lysine N6-myristoyltransferase activity
Biological process: ketone metabolic process; N-terminal peptidyl-glycine N-myristoylation; protein localization to membrane; N-terminal protein myristoylation; positive regulation of establishment of protein localization to mitochondrion; protein myristoylation; regulation of opsin-mediated signaling pathway
Cellular component: cytoplasm; cytosol; membrane; plasma membrane
Genetic constraint (gnomAD): Loss-of-function variants: 11 observed, 57.34 expected, observed/expected ratio (o/e) 0.19, 90% interval 0.12 to 0.32. The upper end of that interval is the gene's LOEUF score, 0.32, which puts it in group 1 of 6, group 1 being the genes least tolerant of losing a copy. Missense variants: 418 observed, 640.98 expected, observed/expected ratio (o/e) 0.65, 90% interval 0.6 to 0.71. Synonymous variants: 223 observed, 237.87 expected, observed/expected ratio (o/e) 0.94, 90% interval 0.84 to 1.05.
Homologues: Orthologues: chimpanzee NMT1 (100% identical), pig NMT1 (99% identical), macaque NMT1 (99% identical), rabbit NMT1 (98% identical), mouse Nmt1 (97% identical), rat Nmt1 (97% identical), guinea pig NMT1 (97% identical), tropical clawed frog nmt1 (82% identical), zebrafish nmt1a (81% identical), Drosophila melanogaster Nmt (54% identical), zebrafish nmt1b (53% identical), Caenorhabditis elegans nmt-1 (47% identical). Paralogues in human: NMT2 (75% identical).
Diseases named in the same sentence as NMT1 in open-access papers:
NMT1 is named in the same sentence as 71 diseases in open-access papers, as found by Europe PMC text mining. Sharing a sentence is not in itself a finding about the gene and the disease. The quoted sentences say what the papers report.
breast carcinoma (16 papers, 2016 to 2025). "In contrast, a recent study showed that NMT1 is highly expressed in breast cancer and associated with aggressiveness." (PMID 40748136, 2025). "The NMT1 gene was highly expressed in the tumor and is reported as a potential diagnostic biomarker in breast cancer related to poor prognosis." (PMID 39239354, 2024). "NMT1 has been reported to be associated with many cancers, including breast cancer, bladder cancer, nonsmall-cell lung cancer, and so on." (PMID 36967718, 2023). "In breast cancer, elevated NMT1 protein levels are associated with high overall histological grade, high Ki67 and low hormone receptor expression." (PMID 37140999, 2023). "Together, these results indicated JNK pathway activation, caused by NMT1 knockdown, was responsible for NMT1 knockdown mediated breast cancer progression delay both in vitro and in vivo." (PMID 30446635, 2018). "Based on these findings, we hypothesized that targeting NMT1 would disrupt lots of protein function, and location, and abrogate normally biological process, causing great damage to breast cancer cellular homeostasis." (PMID 30446635, 2018). "Therefore, NMT1 is a potential diagnostic biomarker for breast cancer." (PMID 37140999, 2023). "We found an association of NMT1 with four aging outcomes: type 2 diabetes, CHF, essential hypertension, and breast cancer." (PMID 40792619, 2025). "Analysis of the TCGA breast cancer cohort showed that NMT1 mRNA expression was reduced compared with normal tissue, although expression levels remained comparable with thyroidal NMT1." (PMID 40748136, 2025). "High expression of NMT1 and Src are associated with thyroid tumour recurrence and PBF and Src are highly expressed in breast cancer, particularly in more aggressive forms." (PMID 40748136, 2025). "It has been reported that the suppression of NMT1 abolishes the function of Src on facilitating prostate cancer advancement, and NMT1 knockdown restrained breast cancer progression via JNK pathway triggered by stress." (PMID 36967718, 2023). "It is similar to the expression of NMT1 in certain human malignancies such as colorectal cancer, prostate cancer, and breast cancer." (PMID 36967718, 2023). "In summary, drug research is necessary to identify NMT1-specific inhibitors for potential therapeutic use in lung and breast cancers." (PMID 37140999, 2023). "In breast epithelial cells, proliferative capacity correlates with NMT activity, and breast cancer patients have elevated NMT1 expression in tissue microarrays." (PMID 37140999, 2023). "NMT1 and RERE were only highly expressed in PH026, and NMT1 was studied widely for breast cancer and showed suppression on initiation, proliferation and invasion of breast cancer cells." (PMID 35865544, 2022). "On the other hand, activation of CASP3 is involved in the initiation of cell apoptosis, inhibition of NMT1 regulates breast cancer oncogenesis by the JNK pathway, and inactive XRCC6 fails to protect genomic integrity." (PMID 32419250, 2020). "To investigate the clinical significance of NMT1, we assessed NMT1 expression in primary breast cancer tissues and adjacent normal breast tissue of 20 patients." (PMID 30446635, 2018). "Next, we searched for the possible mechanisms of how NMT1 regulating breast cancer growth and metastasis." (PMID 30446635, 2018). "The expression of proteins responsible for G2M transition was decreased in NMT1 knockdown breast cancer cell lines." (PMID 30446635, 2018). "In this study, we explored the role and mechanisms of NMT1 in regulating breast cancer initiation, progression and metastasis." (PMID 30446635, 2018). "We treated ER positive breast cancer cells with rapamycin and determined the effect of mTOR inhibition on NMT1 in a time dependent manner." (PMID 30154572, 2018). "Our study suggested that JNK activation promoted not apoptosis but autophagy and up-regulated downstream target p21 to prevent breast cancer progression after NMT1 knockdown." (PMID 30446635, 2018).
breast carcinoma (continued). "ER chaperone BIP and ER sensors (PERK, IRE1A, and ATF6) were upregulated in NMT1 knockdown breast cancer cell lines, suggesting shRNA mediated NMT1 knockdown actually cause ER stress." (PMID 30446635, 2018). "The genetic inhibition of NMT1 triggered ER stress was persisted and prolonged in breast cancer cells, which had promising effects on many other biological aspects." (PMID 30446635, 2018). "In this study, we demonstrated that genetic inhibition of N-myristoyltransferase NMT1 suppressed initiation, proliferation and invasion of breast cancer cells either in vitro or in vivo." (PMID 30446635, 2018). "We here found that inhibition of ROS production via NAC significantly restrained JNK pathway activation in NMT1 knockdown breast cancer cell lines." (PMID 30446635, 2018). "Together, these results suggested knocking down NMT1 inhibited breast cancer progression and metastasis both in vitro and in vivo." (PMID 30446635, 2018). "To explore the function of elevated ROS in NMT1 knockdown breast cancer, we utilized an antioxidant N-acetyl cysteine (NAC) to neutralize ROS." (PMID 30446635, 2018). "And we individually established PERK, IRE1A, and ATF6 knockdown cell lines in NMT1 knockdown breast cancer cells." (PMID 30446635, 2018). "To determine the effect of NMT1 expression on breast cancer, we established shRNA-mediated NMT1 knockdown cell lines in SUM149, MDA-MB-231, HCC1937 and T47D." (PMID 30446635, 2018). "In this study, we demonstrate that NMT1 is capable of modulating breast cancer cell initiation and promoting cell proliferation and invasion through intracellular stress induced JNK pathway activation both in vitro and in vivo." (PMID 30446635, 2018). "Instead, we found that JNK pathway was activated in NMT1 knockdown breast cancer cells and xenograft tumors." (PMID 30446635, 2018). "Together, these results strongly support the role of ER stress as functional downstream mediators of NMT1 knockdown in breast cancer." (PMID 30446635, 2018). "Given the observation that JNK pathway was activated, we needed to elucidate the importance of JNK pathway in breast cancer after NMT1 knockdown." (PMID 30446635, 2018). "Pharmacological inhibition of JNK pathway totally abrogated the accumulation of the lipidated LC3-II form and LC3 puncta in NMT1 knockdown breast cancer cells." (PMID 30446635, 2018). "Knocking down either PERK or IRE1A partially abrogated NMT1 knockdown-mediated decrease of ALDH-positive cell population and mammosphere formation, and partially abrogated NMT1 knockdown-mediated inhibition of migration and invasion in breast cancer cells." (PMID 30446635, 2018). "Several studies suggest that NMT1 activity is important for the progression of different malignancies including breast cancer, oral squamous cell carcinoma, colon carcinoma and gallblader cancer." (PMID 27438140, 2016). "A former work has demonstrated that the knockdown of NMT1 could suppress the initiation, growth, and metastasis of breast cancer." (PMID 36967718, 2023). "While a very high proportion of breast cancer samples had detectable NMT1 protein levels (602 of 666 tumors), a large proportion (509 of 706 tumors) exhibited very low or undetectable amounts of NMT2 despite normal breast epithelia being ubiquitously positive for NMT2 proteins." (PMID 33398478, 2021). "Furthermore, miR-409-3p and miR-106b-3p, and miR-127 that all bind to the NMT1 transcript, have been reportedly involved in colorectal cancer and breast cancer respectively." (PMID 29579063, 2018). "JNK pathway played a key role in NMT1 knockdown breast cancer." (PMID 30446635, 2018). "Taken together, these results indicated NMT1 inhibition could induce oxidative stress to modulate breast cancer initiation and progression." (PMID 30446635, 2018). "And NMT1 knockdown significantly up-regulated ROS level in breast cancer cells, which clearly indicated NMT1 knockdown in breast cancer could also contribute to oxidative stress." (PMID 30446635, 2018).
breast carcinoma (continued). "We have demonstrated that prolonged inhibition of NMT1 could cause poly-ubiquitinated proteins increase, trigger ER stress and oxidative stress, and result in JNK abnormal activation in breast cancer." (PMID 30446635, 2018). "NMT1 level was significantly higher in breast tumor tissues compared to adjacent noncancerous tissues, and was especially increased in triple-negative subtypes of breast cancer." (PMID 30446635, 2018). "Moreover, the decreased ability of migration and invasion of breast cancer via NMT1 knockdown was remarkably inhibited by administration of 4-PBA." (PMID 30446635, 2018). "To investigate what role NMT1 knockdown induced-ER stress has played in regulation of breast cancer progression, we implied pharmacological and genetic inhibition of ER stress in NMT1 knockdown triple-negative breast cancer cells (SUM149, MDA-MB-231, and HCC1937)." (PMID 30446635, 2018). "ROS was produced at higher level in NMT1 knockdown breast cancer cells than shctrl." (PMID 30446635, 2018). "However, we did not see any significant changes in the phosphorylated levels of SFK family kinases via genetic inhibition of NMT1 in breast cancer cells." (PMID 30446635, 2018). "NMT1 knockdown increased level of lipidated LC3 in breast cancer." (PMID 30446635, 2018). "Therefore, in advanced tumours that may benefit from alternative therapies, targeting NIS repression by Src and PBF through NMT1 inhibition may be a viable approach for augmenting RAI-avidity in breast cancer." (PMID 40748136, 2025). "We specifically focused our research on triple-negative breast cancer (TNBC) and found that genetic inhibition of NMT1 triggered both ER stress and oxidative stress, and therefore stimulating the JNK pathway to inhibit breast cancer progression." (PMID 30446635, 2018). "Treatment of breast cancer cells with 4-PBA significantly reduced ER stress both in Shctrl and NMT1 knockdown groups compared to DMSO group." (PMID 30446635, 2018). "To begin our assessment of NMT1 expression in breast carcinoma, we compared the relative expression of NMT1 proteins in normal and cancerous tissue samples using IHC." (PMID 33398478, 2021). "Since the “Compound 1” was not specifically aimed to NMT1 and pharmacological inhibition did not last very long time, we did experiments in our genetic NMT1 inhibiting breast cancer model." (PMID 30446635, 2018). "Furthermore, treatment with a pan-NMT inhibitor, PCLX-001, decreased breast cancer cell viability in vitro and led to a dose-dependent reduction in the growth of MDA-MB-231 breast cancer xenografts, demonstrating significant NMT1 activity and supporting potential clinical utility in breast cancer." (PMID 40748136, 2025). "We found that NMT1 protein levels correlated with poor prognosis in general and that NMT2 protein could not be detected in the majority of breast cancer samples and when it was detected it was linked with a poorer prognosis." (PMID 33398478, 2021). "Since altered expression of protein kinase B (PKB)/Akt in breast cancer cells affect N-myristoyltransferase 1 (NMT1) expression and activity, we investigated whether mTOR, a downstream target of PKB/Akt, regulates NMT1 in ER positive breast cancer cells (MCF7 cells)." (PMID 30154572, 2018).
malaria (10 papers, 2014 to 2025). Malaria is a serious and sometimes fatal disease caused by a parasite that commonly infects a certain type of mosquito which feeds on humans. "Due to their essential roles, NMT-1 and 2 have been recognized as plausible targets for the treatment of various diseases like leishmaniasis, ischemia-reperfusion injury, malaria, inflammation, Chagas disease, fungal infections, etc.." (PMID 33805223, 2021).
melanoma (6 papers, 2013 to 2021). A malignant, usually aggressive tumor composed of atypical, neoplastic melanocytes. "As previously reported, Tris DBA has been shown to inhibit MAPK, PKC, and AKT pathways in melanoma as a result of NMT-1 blockade." (PMID 31320995, 2019). "Tris(dibenzylideneacetone)dipalladium (Tris DBA-Pd) is a novel inhibitor of N-myristoyltransferase 1 (NMT-1) and has proven in vivo activity against melanoma." (PMID 30824801, 2019). "First generation NMT-inhibitors such as Tris dibenzylidenacetone dipalladium (Tris DBA) inhibited NMT1 with IC50 = 1.0 μM in vitro, blocked MAPK and Akt signaling in cells, and demonstrated anti-tumor activity in a mouse melanoma model." (PMID 23824448, 2013).
ovarian carcinoma (6 papers, 2018 to 2024). A malignant neoplasm originating from the surface ovarian epithelium. "For ovarian cancer susceptible to drug resistance, the intersecting roles of NMT1 and Src signaling indicate that a new therapeutic strategy could involve the combination of NMT1 inhibitors with anticancer drugs." (PMID 38338729, 2024). "Furthermore, higher NMT1 mRNA levels are associated with poorer patient prognosis in ovarian cancer." (PMID 37140999, 2023). "Ovarian cancer metastases have higher NMT1 protein levels than paired ovarian primary cancers, and aggressive ovarian cancers have higher levels of Src, suggesting a possible mechanism for zelenirstat activity in this disease." (PMID 38837078, 2024). "The morphology of the two KO clones was indistinguishable from wt HAP1 cells, although the NMT1 KO cells grew somewhat slower mirroring the effect of siRNA-mediated HsNMT1 knockdown in ovarian cancer cells." (PMID 30080883, 2018). "The effects of NMT1 on cancer development are extensive, especially in colon, lung, breast and ovarian cancers, and involve proto-oncogene tyrosine-protein kinase Src signalling and mechanisms of cellular metabolism (mitochondria, lysosomes), endoplasmic reticulum (ER) stress and lipid recoding." (PMID 37140999, 2023). "Indeed, compared to normal tissues, NMT2 expression was significantly decreased in multiple tumor types (9/11) and metastatic tissues, including breast, lung, colon, and ovarian cancers, whereas NMT1 expression was significantly increased in multiple tumor types (8/11), and metastases." (PMID 38715059, 2024). "Given the converging role of NMT1 in AMPK and the Src pathway, for ovarian cancers prone to metastasis or drug resistance, the combination of NMT1 inhibitors and existing drugs may provide a new therapeutic avenue." (PMID 37140999, 2023). "Increased myristate acid levels can enhance AMPK signalling in ovarian cancer cells because of myristoylation of the AMPK β-subunit (AMPKβ is specifically regulated by NMT1 rather than NMT2)." (PMID 37140999, 2023). "However, suppression of both NMT1 and NMT2 can induce apoptotic effect on ovarian cancer cell line, SK-OV-3, with NMT2 inhibition showing greater apoptotic effect compared with NMT1." (PMID 34095144, 2021).
colon carcinoma (5 papers, 2007 to 2024). "Given the elevated expression and activity of Src in prostate and colon cancers, targeting the NMT1–Src axis provides a novel approach to inhibit tumour progression, particularly in Src-driven tumours." (PMID 37140999, 2023). "In addition, high-scoring MISS-54 hematologic, testicular, and colon cancers were among the cancers most dependent on NMT1 in DepMap while kidney cancer was NMT1-independant and had the lowest MISS-54 score." (PMID 38715059, 2024).
colorectal cancer (5 papers, 2007 to 2026). A primary or metastatic malignant neoplasm that affects the colon or rectum. "Bladder, head and neck, and colorectal cancers also exhibited higher than median NMT1 dependency scores, with kidney cancer being the least affected by NMT1 KO." (PMID 38715059, 2024). "In DLD-1 (colorectal cancer) and RPE-1 (non-transformed, near-diploid retinal pigment epithelium), co-depletion of DCAF10 with NMT1/2 increased Lyn, Fyn, and Src relative to NMT1/2 knockdown (KD) alone." (PMID 41484149, 2026).